ACVRL1 (activin A receptor like type 1)
Diseases named in the same sentence as ACVRL1 in open-access papers (continued):
Sharing a sentence is not in itself a finding about the gene and the disease.
Pulmonary arteriovenous malformation (4 papers, 2009 to 2023). Pulmonary arteriovenous malformation, a condition most commonly associated with hereditary hemorrhagic telangiectasia, is an abnormal communication between the pulmonary artery and pulmonary vein without an intervening capillary communication. "ENG patients were significantly younger at diagnosis (36.9 vs 45.7 years) and had pulmonary arteriovenous malformations (AVMs) (71.4% vs 24.4%) and cerebral AVMs (17.6% vs 2%) more often than patients with ACVRL1 variants." (PMID 32503579, 2020). "The phenotypic expression of the disease depends on the mutated gene: for instance, patients with ENG mutations (“HHT1 phenotype”) are more likely to have pulmonary arteriovenous malformations (PAVMs) than patients with ACVRL1 mutations (“HHT2 phenotype”)." (PMID 24603803, 2014). "The genotype-phenotype correlation was consistent with a higher frequency of pulmonary arteriovenous malformations in patients with ENG mutations than in patients with ACVRL1 mutations in our collective." (PMID 19508727, 2009).
COVID-19 (3 papers, 2021 to 2023). A disease caused by infection with severe acute respiratory syndrome coronavirus 2. "Of the 107 patients with ascertained COVID-19, 50 had a known genetic mutation in ENG (18/50), ACVRL1 (31/50) or SMAD4 (1/50)." (PMID 37140873, 2023). "Among the 50 COVID-19 patients with identified disease-causing mutation, hospitalization was needed in four cases, represented by one ENG-mutated patient and three ACVRL1-mutated patients, two of the latter requiring intensive care monitoring." (PMID 37140873, 2023). "In the 9 ascertained COVID-19 patients, the HHT-causing mutation was located in the ENG gene (HHT1) and in the ALK1/ACVRL1 gene (HHT2) in 3 and 6 patients, respectively, thus resulting in an overlapping distribution with the COVID-19-free patients." (PMID 34496900, 2021). "COVID-19 immune response and SZ share one DEG (activin A receptor type II-like 1, or ACVRL1) that is upregulated and two DEGs (CXCR2, CXCL1) that are both downregulated, all of which are strongly associated with the pathogenesis of COVID-19." (PMID 35185890, 2022).
lung adenocarcinoma (3 papers, 2021 to 2026). A carcinoma that arises from the lung and is characterized by the presence of malignant glandular epithelial cells. "We screened and verified four differentially expressed BMPs (BMP2, BMP5, BMP6, and GDF10) and one BMPR (ACVRL1), which all were downregulated in lung adenocarcinoma tissues." (PMID 34745928, 2021). "Notably, a study showed that Hsa_circ_0129047 regulates the miR-375/ACVRL1 axis to slow the progression of lung adenocarcinoma." (PMID 41579221, 2026). "Finally, SFTPA1, PLXNB3, BIRC5, CBLC, and ACVRL1 were screened out based on the intersection between the top 10 differentially expressed genes in lung adenocarcinoma (LUAD) and lung squamous cell carcinoma (LUSC)." (PMID 34181042, 2022). "BMP2, BMP5, BMP6, GDF10, and ACVRL1 were verified as downregulated in lung adenocarcinoma." (PMID 34745928, 2021).
breast tumor (2 papers, 2019 to 2023). "To conclusively demonstrate a direct association between ACVRL1 and CLEC14A expression, we performed simultaneous RNAscope in situ hybridization on human breast tumor specimens." (PMID 30132150, 2019).
capillary malformation (2 papers, 2021 to 2025). "If only ENG and ACVRL1 genes are investigated diagnosis of HHT or capillary malformation-arteriovenous malformation syndrome (HHT-like syndrome) may be delayed or they may remain undiagnosed." (PMID 33807613, 2021).
gastric cancer (2 papers, 2013 to 2022). A primary or metastatic malignant neoplasm involving the stomach. "In gastric cancer, we found CTHRC1 was highly co-expressed with many factors, such as ACVRL1, ANGPTL3, ANGPTL4, NOTCH4, VEGFB, VEGFC etc., which have been proved to play an important role in angiogenesis in various cancer." (PMID 35928443, 2022).
liver disease (2 papers, 2020). "Similar to previous studies, among patients with genotype data available from our cohort, those at high risk of harboring clinically significant liver disease had ACVRL1 mutation." (PMID 32122373, 2020). "In fact, in two studies including patients with genotype data available, those who developed symptomatic liver disease had ACVRL1 mutation." (PMID 32503579, 2020).
melanoma (2 papers, 2020 to 2025). A malignant, usually aggressive tumor composed of atypical, neoplastic melanocytes. "In this respect, inspection of the longitudinal scRNA-Seq human melanoma dataset confirms that ACVRL1 expression follows that of PD-L1 and PD-L2." (PMID 39808498, 2025).
metastatic colorectal cancer (2 papers, 2022 to 2023). "The overexpression of the ACVRL1 gene in metastatic colorectal cancer patients treated with bevacizumab-based chemotherapy was shown to enhance progression-free survival and overall survival." (PMID 37175499, 2023).
non-small cell lung carcinoma (2 papers, 2014 to 2026). A group of at least three distinct histological types of lung cancer, including non-small cell squamous cell carcinoma, adenocarcinoma, and large cell carcinoma. "An entity screen in non-small cell lung cancer cells A549 identified the target gene ACVRL1 that produces expression changes in response to drug treatment." (PMID 41579221, 2026).
prostate carcinoma (2 papers, 2017 to 2018). A carcinoma that arises from epithelial cells of the prostate gland. "These include MMP8, a metallopeptidase that contributes to extracellular matrix remodeling, NAALAD2, a peptidase that hydrolyses N-acetyl-aspartyl glutamate and glutamate and a marker of prostatic carcinomas, and ACVRL1, a receptor for TGF-β family of ligands." (PMID 29608722, 2018).
alveolar capillary dysplasia (1 paper, 2022). "BMP9 receptor, ACVRL1, and its downstream target genes were inhibited in EPCs from Foxf1WT/S52F mutant mice, a model of alveolar capillary dysplasia with misalignment of pulmonary veins (ACDMPV)." (PMID 35440116, 2022).
Autoimmunity (1 paper, 2020). The occurrence of an immune reaction against the organism's own cells or tissues. "Transcriptome group 3 (ACVRL1, CD93, CEBPB, NINJ1, SRGN) encodes preferentially for proteins related to autoimmunity." (PMID 32325790, 2020).
bleeding (1 paper, 2022). "The absence of PAVMs and the presence of nasal, gastric bleeding and HAVMs suggested a higher possibility for having an ACVRL1/ALK1 mutation." (PMID 35683441, 2022).
Childhood onset (1 paper, 2023). Onset of disease at the age of between 1 and 5 years. "ACVRL1 p.Arg484Gln has also been identified in HHT295 and in childhood-onset pulmonary arterial hypertension." (PMID 37978175, 2023).
clear cell renal carcinoma (1 paper, 2019). A malignant epithelial neoplasm of the kidney characterized by the presence of lipid-containing clear cells within a vascular network. "In contrast, higher expression of ACVRL1 was a distinguishing feature of glioblastoma multiforme (GBM) and clear cell renal carcinoma (KIRC)." (PMID 30132150, 2019).
emphysema (1 paper, 2012). "The expression of CD79A, a component of the B-cell receptor, increased in expression with increasing emphysema severity, and the expression of ACVRL1 (also known as activin-like kinase I), a receptor in the TGFβ pathway, decreased in expression with increasing emphysema severity." (PMID 22937864, 2012). "The changing expression of SMAD6 and SMAD1, their localization predominantly to vascular endothelial cells, and the roles of ACVRL1 and ENG in angiogenesis support the hypothesis of aberrant tissue remodeling in the lung vasculature during emphysema pathogenesis." (PMID 22937864, 2012).
endothelial dysfunction (1 paper, 2015). In vascular diseases, endothelial dysfunction is a systemic pathological state of the endothelium (the inner lining of blood vessels) and can be broadly defined as an imbalance between vasodilating and vasoconstricting substances produced by (or acting on) the endothelium. "The underlying mechanism of HHT1 and HHT2 is haploinsufficiency indicating that reduced amounts of ENG and ACVRL1 lead to endothelial dysfunction and predispose to the clinical signs of disease." (PMID 25763011, 2015).
epithelial ovarian cancer (1 paper, 2019). "Altered BMP signalling in ovarian cancer was also observed in epithelial ovarian cancer cells since autocrine BMP9, which usually signals through ACVRL1, also signals through ACVR1, increasing the phosphorylation of SMAD1/5 and promoting ovarian cancer cell proliferation." (PMID 31683698, 2019).
head and neck cancer (1 paper, 2017). A primary or metastatic malignant neoplasm affecting the head and neck. "One of these genes, ACVRL1 correlated with tumour progression in patients with head and neck cancers; whereas two other genes: ZFYVE21, and CLEC3B were related to cancer invasiveness." (PMID 28574441, 2017).
Hypercholesterolemia (1 paper, 2016). An increased concentration of cholesterol in the blood. "Here we characterize one of these hits in detail, ACVRL1 (also called ALK1) which fulfils the criteria for a novel low-affinity, high-capacity receptor for LDL in endothelial cells that functions during hypercholesterolemia and promotes LDL transcytosis." (PMID 27869117, 2016).
Hypertension (1 paper, 2019). The presence of chronic increased pressure in the systemic arterial system. "Common gene mutation sites were analyzed to investigate the the association between single nucleotide polymorphisms (SNPs) of the BMPR2, ACVRL1, and SMAD9 genes with hypertension risk." (PMID 30617053, 2019).
lymphoid tumors (1 paper, 2012). "Expression of ACVRL1 mRNA was detected in the two thymic lymphomas with flit-1 rearrangement, whereas normal thymuses and seven lymphoid tumors without flit-1 rearrangement had no detectable ACVRL1 mRNA expression." (PMID 23202500, 2012).
lymphoma (1 paper, 2024). A malignant (clonal) proliferation of B- lymphocytes or T- lymphocytes which involves the lymph nodes, bone marrow and/or extranodal sites. "For BMP receptors, the expression of BMPR1B and ACVRL1 was barely detectable in lymphoma cells." (PMID 38229201, 2024).
myocardial infarction (1 paper, 2025). Gross necrosis of the myocardium, as a result of interruption of the blood supply to the area, as in coronary thrombosis. "We also used thalidomide for a 70-year-old male patient with an ACVRL1 mutation, who previously did not have severe epistaxis unless having a myocardial infarction." (PMID 41303195, 2025).
Parkes Weber syndrome (1 paper, 2023). "Cutaneous vascular lesions are a common hallmark of developmental vascular disorders such as RASA1- and EPHB4-mutated CM-AVM25,27, ENG1- and ACVRL1-mutated HHT29, and RASA1-mutated Parkes Weber syndrome, among others." (PMID 37978175, 2023).
pulmonary fibrosis (1 paper, 2015). Chronic progressive interstitial lung disorder characterized by the replacement of the lung tissue by connective tissue, leading to progressive dyspnea, respiratory failure, or right heart failure. "Furthermore, several genes that were significantly co-expressed with PEAR1 have also been previously implicated in endothelial-related pathological conditions including pulmonary fibrosis (CTGF) and hemorrhagic telangiectasia (ACVRL1 and ENG)." (PMID 26406321, 2015).
sarcoma (1 paper, 2021). A usually aggressive malignant neoplasm of the soft tissue or bone. "The molecular characteristics of the four molecular subtypes were compared, and we determined three genes, namely, ENO1, ACVRL1 and APBB1IP, which were closely associated with the prognosis of sarcoma." (PMID 33509178, 2021). "RT-qPCR assay results indicated that ENO1 was upregulated, whereas ACVRL1 and APBB1IP were downregulated in Hs 729 sarcoma cells that in 10.014 pRSV-T cells." (PMID 33509178, 2021). "Furthermore, the three potential prognostic markers (ENO1, ACVRL1 and APBB1IP) in predicting the sarcoma prognosis of different histological types were examined, due to the sample sizes of DT, MPNST, and SS, the prognostic role of the three genes were analyzed in DL, LMS, MFS and UPS." (PMID 33509178, 2021).
tumor (25 papers, 2014 to 2026). "More recently, we determined that the network of genes correlated with ACVRL1 expression is associated with a series of processes defining the tumor microenvironment (TME) across human solid malignancies, with a large overrepresentation of pathways linked to immune cell function and regulation." (PMID 39808498, 2025). "The use of computational analysis enabled the generation of cancer-specific sets of genes associated with ACVRL1 expression that could be further refined to obtain a single list of common factors conserved across different tumor types." (PMID 30132150, 2019). "Except for KIRC, the remaining tumor types all showed a broad range of ACVRL1 mutations." (PMID 30132150, 2019). "For expression of genes involved in vascular morphogenesis and maturation, it was reported that low VEGFB and high FLT1 in primary tumours and high ACVRL1 levels in liver metastases were associated with enhanced OS of CRC patients with liver metastases treated with bevacizumab plus chemotherapy." (PMID 29535825, 2018). "This regulation transcends the specific requirements dictated by tumor evolution and holds a broader relevance for pathologies that rely on hematopoietic dysfunction for their medical evolution, including the human hemorrhagic telangiectasia that is caused by congenital mutations in ACVRL1." (PMID 39808498, 2025). "To further explore this, we analyzed the expression of ACVRL-1, the phosphorylation levels of Smad1/5/9, and the expression of ID-1 in tumor tissues." (PMID 41579221, 2026). "Inhibition of ACVRL1 expression in transgenic tumour-bearing mice or treatment with ALK1-Fc fusion protein RAP-041 inhibits angiogenesis to delay tumour growth and progression." (PMID 41579221, 2026). "In this study, BYJHD inhibited the transcriptional level of ACVRL1 in the A549 cell line and the expression of ACVRL1 protein in tumour-bearing mice." (PMID 41579221, 2026). "In clinical studies, the ligand trap (dalantercept) and the monoclonal antibody PF-03446962 of ACVRL1 have demonstrated desirable anti-tumour efficacy." (PMID 41579221, 2026). "Taken together, our data reveal that expression of ALK1 is not, as previously reported, exclusive for the endothelium and that a population of recruited TAMs is also characterized by ACVRL1 expression across human breast malignancies." (PMID 39808498, 2025). "Through integration of in vivo platforms, ex vivo assays and longitudinal in silico data, we demonstrate that Acvrl1+ TAMs derived from circulating CD14+ monocytes that were recruited to the tumor site." (PMID 39808498, 2025). "Pharmacological targeting ACVRL1 by using anti-ACVRL1 antibody or a ligand-trapping agent can inhibit tumour growth and metastasis in preclinical models." (PMID 37743483, 2023). "In vivo experiments, the growth of tumours from ACVRL1-knockdown HCT15 cells was completely retarded after mTKI treatment, leading to lower tumour weight and volume than the control group." (PMID 37743483, 2023). "By performing IHC testing on multi-cancerous tissue microarray, we found that the expression of ACVRL1 is significantly higher in CRC when compared with most mTKI-sensitive tumours (HCC, RCC, etc.)." (PMID 37743483, 2023). "In this study, we developed a novel angiogenesis score and feature genes (MMRN2, CLEC14A, ACVRL1, EFNB2, and TEK) which was associated with tumor angiogenesis microenvironment and prognosis in KIRC patients." (PMID 33761933, 2021). "In tumor samples, tissues from different origins displayed generally more heterogeneous levels of ACVRL1 in endothelial cells." (PMID 30132150, 2019). "When this method was applied to the entire collection of the TCGA repository, ACVRL1 expression levels showed close association to the reference endothelial MCP-counter score in both normal and tumor tissues, with R equal to 0.7 and 0.678, respectively." (PMID 30132150, 2019). "Our cross-cancer analysis highlights a variable, but consistent, expression of ACVRL1 in all tumor types." (PMID 30132150, 2019).
tumor (continued). "Next, ranked lists of ACVRL1-correlated genes with a Pearson coefficient ≥ 0,5 were generated and used to determine the commonality of gene regulation instigated by ACVRL1 expression across tumor types." (PMID 30132150, 2019). "Anti-tumour strategies targeting ACVRL1 are also gradually attracting academic attention." (PMID 41579221, 2026). "In summary, we speculate that BYJHD exerts its anti-NSCLC activity through the ACVRL-1/Smad/ID-1 axis and the inhibition of CD expression, thereby regulating the tumour microenvironment and inhibiting tumour angiogenesis." (PMID 41579221, 2026). "Although several proteins (e.g., ACVRL1, DUSP4, PREX1) showed increased expression in the high-risk group, PD-L1 and p38 MAPK were prioritized for mechanistic validation due to their established roles in tumor-immune interactions." (PMID 41050683, 2025). "IHC staining also indicated this regulatory effect of ACVRL1 on GPX2 in tumour xenografts." (PMID 37743483, 2023). "Given the limited benefit shown by ALK1-blocking agents in clinical trials, we asked whether the expression status of the components of the signaling complex centered around ACVRL1 delineates tumor types that would benefit from ALK1 inhibition." (PMID 30132150, 2019). "In particular, the reduced levels of ACVRL1 compared to the corresponding normal tissues suggest the inability of the proliferating malignant mass to develop a vascular tree to adequately sustain the metabolic needs of the tumor cells." (PMID 30132150, 2019). "Future work should include genetic or pharmacological inhibition of ACVRL1 to determine whether its suppression alone recapitulates the anti-tumor and anti-angiogenic effects of BYJHD, thereby confirming its indispensable role in mediating therapeutic outcomes." (PMID 41579221, 2026). "It was shown that the expression of BMP8B was significantly increased in tumour compared with normal tissues, while BMP6 and ACVRL1 were expressed at lower levels." (PMID 37333824, 2023). "The violin plot describing the distribution of BMP expression in tumor and normal tissues suggested that GDF10 was the most significantly downregulated BMP, and the downregulating degree of ACVRL1 was obvious from the violin plot of BMPRs." (PMID 34745928, 2021). "The size of the tumor also affected the expression of BMP3 (P = 0.0047), BMP7 (P = 0.0210), BMPR1B (P = 0.0460), ACVR2A (P = 0.0350), ACVRL1 (P = 0.0045), TGFBR2 (P = 0.0170), and TGFBR3 (P = 0.0150) according to the K-W test." (PMID 34036102, 2021). "In the setting of tumor angiogenesis, genetic or pharmacologic targeting of ALK1 (gene name Acvrl1) results in a significant growth delay and angiogenic blockade." (PMID 27741515, 2016). "BYJHD can down-regulate the phosphorylation of Smad protein by inhibiting the expression of tumour ACVRL1, and reduce the expression of the target gene ID-1 and the surface marker CD34 in the tumour microenvironment to regulate tumour angiogenesis, leading to anti-NSCLC effects." (PMID 41579221, 2026). "ACVRL1 and KAT2A are the only two nodes with low correlation to tumor purity (FDR > 0.001)." (PMID 40228208, 2025). "Meanwhile, IHC and ISH staining indicated that ACVRL1 had no regulatory effect on miR-7-5p in tumour xenografts treated with Regorafenib." (PMID 37743483, 2023). "To investigate the tumor promoting effect of BMP signaling in EC, we further performed in vitro experiments using Ishikawa EC cells, revealing expression of mRNA for all type I and type II BMP receptors, except ACVRL1." (PMID 34360647, 2021). "Some of these proteins were tumor suppressors, including Rb, FOXO3, and p27, and many proteins were kinases and involved in the regulation of cell proliferation, differentiation, and apoptosis, such as c-KIT, AKT, EGFR, MAPK1/3, PRKCA, SRC, ACVRL1, and JNK2." (PMID 32917965, 2020).